MON1B (MON1 vesicular trafficking associated B)
Synonyms: HSRG1; KIAA0872; SAND2; SRG1
Tractability: PROTAC: ubiquitination databases record sites on it; its protein half-life has been measured.
Gene: Protein-coding gene on chromosome 16 (77,190,835 to 77,202,398, forward strand). Ensembl gene ENSG00000103111.
Subcellular location (Human Protein Atlas): Cytosol
Pathways (Reactome):
Vesicle-mediated transport: RAB GEFs exchange GTP for GDP on RABs
Gene Ontology:
Molecular function: protein binding; guanyl-nucleotide exchange factor activity
Biological process: early viral transcription; late viral transcription; protein targeting to vacuole; vesicle-mediated transport
Cellular component: cytoplasm; late endosome; Mon1-Ccz1 complex
Genetic constraint (gnomAD): Loss-of-function variants: 26 observed, 45.31 expected, observed/expected ratio (o/e) 0.57, 90% interval 0.42 to 0.8. The synonymous counts are far from expectation, so gnomAD's model fits this gene poorly and the ratio says little. Missense variants: 737 observed, 773.34 expected, observed/expected ratio (o/e) 0.95, 90% interval 0.9 to 1.01. Synonymous variants: 395 observed, 328.83 expected, observed/expected ratio (o/e) 1.2, 90% interval 1.11 to 1.31.
Homologues: Orthologues: chimpanzee MON1B (99% identical), macaque MON1B (97% identical), rabbit MON1B (90% identical), dog MON1B (90% identical), pig MON1B (89% identical), guinea pig MON1B (89% identical), mouse Mon1b (89% identical), rat Mon1b (89% identical), zebrafish mon1bb (50% identical), zebrafish mon1ba (46% identical), Drosophila melanogaster Mon1 (32% identical), Caenorhabditis elegans sand-1 (23% identical). Paralogues in human: MON1A (42% identical).
Diseases named in the same sentence as MON1B in open-access papers:
MON1B is named in the same sentence as 4 diseases in open-access papers, as found by Europe PMC text mining. Sharing a sentence is not in itself a finding about the gene and the disease. The quoted sentences say what the papers report.
cervical tumors (1 paper, 2025). "In cancer, both MON1B and CCZ1 are implicated in the progression of colorectal and cervical tumors, promoting cell proliferation, migration, and invasion." (PMID 40979223, 2025).
colon cancer (1 paper, 2022). "Mon1b is elevated in colon cancer, with its knockdown in vitro leading to a reduction of proliferation, migration, and invasion." (PMID 37066112, 2022).
infection (1 paper, 2023). The state of being infected such as from the introduction of a foreign agent such as serum, vaccine, antigenic substance or organism. "Because CCZ1 is in complex with MON1 (itself formed by MON1A and MON1B), we knocked out MON1A and MON1B respectively and assessed for infection with VSVΔG/MARVGP." (PMID 37880247, 2023). "The knockout of any of these proteins lead to an important drop in infection (89.4% for MON1A and 82.4% for MON1B), also partially recovered when the cells are transcomplemented." (PMID 37880247, 2023).
MON1B also shares sentences with these, for which no sentence is quoted: cancer (1 paper).